MMP2 (matrix metallopeptidase 2)
Diseases named in the same sentence as MMP2 in open-access papers (continued):
Sharing a sentence is not in itself a finding about the gene and the disease.
asbestosis (2 papers, 2017). A lung disorder caused by inhalation of asbestos fibers. "The serum KL-6 and MMP-2 concentrations were highest in patients with asbestosis, particularly in comparison with those in DEWs and HCs (P<0.05)." (PMID 29149883, 2017). "In addition, the serum SP-D and MMP-2 concentrations were negatively correlated with the DLCO % predicted in patients with asbestosis." (PMID 29149883, 2017). "MMP2 and MMP9 were correlated with each other in all groups, except for the asbestosis group." (PMID 28348451, 2017). "Our work also found that the protein levels of both MMP2 and MMP9 were not correlated with levels of HMGB1 in sera of patients with asbestosis or MM." (PMID 28348451, 2017). "Interestingly, both MMP2 and MMP9 serum levels were not correlated with HMGB1 in ARDs, including PP, asbestosis and MPM." (PMID 28348451, 2017).
Ascites (2 papers, 2021 to 2025). Accumulation of fluid in the peritoneal cavity (between the layers of the peritoneum that lines the abdomen). "Some studies suggest that interplay between VEGF and MMP-2 contributes to ascites accumulation, while others highlight the role of VEGF and MMP-9 in this process." (PMID 41009634, 2025).
asphyxia (2 papers, 2024 to 2025). A state of general hypoxia and hypercapnia (abnormally elevated carbon dioxide (CO2) levels in the blood), resulting in acidosis, which affects all tissues in the body. "In this study, we examined clinical characteristics, neuroimaging findings, and MMP2 gene polymorphisms in relation to CP development after perinatal asphyxia." (PMID 41464177, 2025). "This study explored the potential link between MMP2 promoter polymorphisms and the development of CP in children with a history of perinatal asphyxia." (PMID 41464177, 2025). "Therefore, this study aims to investigate the potential association between MMP2 promoter SNPs (−1575G/A (rs243866), −1306C/T (rs243865), and −790T/G (rs243864)) and CP onset, comorbidities, and neurodiagnostics in children with a history of perinatal asphyxia." (PMID 41464177, 2025).
basal cell carcinoma (2 papers, 2016 to 2021). A carcinoma involving the basal cells. "The aim of this study was to compare the expressions of mRNA for metalloproteinases (MMP-2 and MMP-9) and type IV collagen in two different histological types of basal-cell carcinoma (BCCs; nodular and infiltrative) and in normal tissues from the tumor interface." (PMID 27406386, 2016).
Bilharziasis (2 papers, 2010 to 2024). "Taking the etiology into consideration, we could demonstrate that patients with viral etiology had significantly higher serum MMP-2 levels than the controls, whereas in patients with bilharziasis, the serum level of MMP-2 was comparable to that of the controls." (PMID 27942306, 2010). "We measured serum levels of TGF-β1, collagen IV, laminin, MMP-2 and EGF-R, in 50 children with chronic liver disease (HBV, HCV and Bilharziasis) and 30 healthy controls, and determined their relationship to frequently used liver function tests and liver biopsy findings in patients." (PMID 27942306, 2010).
Binswanger disease (2 papers, 2020 to 2022). "Reduced MMP-2 index and elevated albumin index were also able to reliably predict the development of Binswanger disease in VCI." (PMID 32340195, 2020).
bipolar disorder (2 papers, 2020 to 2022). A disorder of the brain that causes unusual shifts in mood, energy, activity levels and the ability to carry out day-to-day tasks. "MMP-9 and MMP-2 expression in blood were not different between patients with bipolar disorder and control group." (PMID 35370878, 2022).
bowel cancers (2 papers, 2013 to 2022). "As a showcase, matrix metallopeptidase 2 (MMP-2), which is highly expressed in the most of tumors, namely, breast, prostate, and bowel cancers, is selected as the target protein." (PMID 35495937, 2022). "ROCK-2 has been localized to invadopodia in intestinal cancer cells and siRNA-mediated knock-down of ROCK reduced MMP-2 activity and invasion." (PMID 23940598, 2013).
bronchiolitis obliterans organizing pneumonia (2 papers, 2005 to 2016). "Gene expression profiling of human and murine organizing pneumonia lesions showed in part comparable expression levels of pivotal genes, notably of TGFB1/Tgfb1, TIMP1/Timp1, TIMP2/Timp2, COL3A1/Col3a1, CXCL12/Cxcl12, MMP2/Mmp2 and IL6/Il6." (PMID 27282780, 2016).
bronchopulmonary dysplasia (2 papers, 2014 to 2024). Bronchopulmonary dysplasia is a chronic respiratory disease that results from complications related to lung injury during the treatment of infant acute respiratory distress syndrome in low-birth-weight premature infants or from abnormal lung development in older infants. "Low MMP-2 level at birth have been associate with the development of bronchopulmonary dysplasia (BPD)." (PMID 38331745, 2024).
Burkitt lymphoma (2 papers, 2007 to 2017). A rare form of malignant mature B-cell non-Hodgkin lymphoma. "In previous studies, it has been reported that PEG10 could induce migration of Burkitt’s lymphoma cells via upregulation of MMP-2 and MMP-9." (PMID 28193232, 2017).
carcinoma in situ (2 papers, 2012 to 2022). "MMP2 and MMP9 were highly expressed in the MIBC tissue compared with carcinoma in situ tissue, suggesting that MMP2 and MMP9 are diagnostic markers for detecting MIBC." (PMID 35449123, 2022). "Microarray analysis of BC profiles (GDS1479) in GEO confirmed that MMP2 and MMP9 mRNA level in MIBC tissues was remarkably increased compared with that in carcinoma in situ tissues." (PMID 35449123, 2022).
carpal tunnel syndrome (2 papers, 2013 to 2016). Entrapment of the median nerve in the wrist that is characterized by numbness, tingling and painful movement. "Hirata and colleagues have previously shown increased MMP2 in flexor tendosynovial tissues collected from patients with carpal tunnel syndrome, with higher MMP2 activity in patients with a sudden exacerbation of symptoms." (PMID 24015193, 2013). "Studies have shown increased MMP-1 or MMP-2 with chronic loading of tendons in tendons with signs of overuse injury and in flexor tendosynovial tissues collected from patients with carpal tunnel syndrome." (PMID 26781840, 2016).
cerebral malaria (2 papers, 2017 to 2021). A sequestration of Plasmodium falciparum in the brain, which can cause coma and/or seizures. "Similarly, in cerebral malaria, MMP-2 and MMP-9 were overexpressed as soon as 8 days p.i., with evidences of MMP-9 activation." (PMID 28814754, 2017).
cervical adenocarcinoma (2 papers, 2010 to 2023). An adenocarcinoma arising from the cervical epithelium. "In the cervix, it was shown that MMP-2, -3 and -9 are present in the tissue of cervical adenocarcinomas, whereas no expression of these MMPs could be detected in the nonneoplastic endocervical epithelium." (PMID 20942921, 2010).
cervical intraepithelial neoplasia (2 papers, 2022 to 2023). "Studies of cervical tissues with cervical intraepithelial neoplasia and invasive squamous cell carcinomas (tested for HPV expression) have shown that the expression of MMP-2 in preinvasive lesions and MMP-1 and MMP-2 in invasive cancer suggests a gradual increase in the potential of cancer invasion." (PMID 35804810, 2022).
choroidal neovascularization (2 papers, 2014 to 2016). An eye disorder described by the growth of new blood vessels that originate from the choroid through a break in the Bruch membrane into the sub–retinal pigment epithelium (sub-RPE) or subretinal space. "Previous reports have indicated that matrix metallopeptidase-2 (MMP-2) regulates angiogenic processes, which are involved in choroidal neovascularization (CNV)." (PMID 24886609, 2014). "Absence of MMP-2 and MMP-9 inhibits experimental choroidal neovascularization." (PMID 26872030, 2016).
chronic asthma (2 papers, 2023). An asthma that is characterized by the development of persistent airway inflammation and recurrent attacks of breathlessness and wheezing, which vary in severity and frequency. "Similarly, the chronic asthma-induced expressions of MMP-2, MMP-9, and COX-2 were strongly suppressed by BIBF1000 treatment." (PMID 36755351, 2023).
chronic cystitis (2 papers, 2024). Recurrent infections of the urinary bladder. "MMP‐2 is involved in the epigenetic onset of chronic cystitis in vivo via DNA methylation changes." (PMID 39723046, 2024).
chronic pancreatitis (2 papers, 1996 to 2008). A chronic inflammatory process causing damage and fibrosis of the pancreatic parenchyma. "This could be particularly important not only in terms of invasiveness but also for influencing the distorted balance of matrix synthesis and degradation, since it is known that increased levels of MMP-2 (not only in chronic pancreatitis) facilitate the deposition of pathological fibrillar collagen." (PMID 18301776, 2008).
chronic venous insufficiency (2 papers, 2014 to 2022). Chronic form of venous insufficiency (disease). "In a follow-up study of rat chronic venous insufficiency segments exposed to increased tension, the same group demonstrated increased MMP-2 and MMP-9, and reduced contractility of the vein segment." (PMID 25520775, 2014). "In the skin of patients affected by severe chronic venous insufficiency (CVI), an elevated gene expression for MMP-1, MMP-2, MMP-9, and MMP-13 has been demonstrated." (PMID 35456498, 2022). "Multiple studies have confirmed increased levels of tissue and plasma MMPs in chronic venous insufficiency, including MMP-1, MMP-2, MMP-3, MMP-9, and MMP-13." (PMID 25520775, 2014).
cleft lip (2 papers, 2022 to 2023). Congenital defect in the upper lip where the maxillary prominence fails to merge with the merged medial nasal prominences. "The aim of this study was to evaluate single nucleotide polymorphisms (SNPs) in FOS, CASP8 and MMP2 and to determine their SNP-SNP interactions with CRISPLD2 variants in the risk of nonsyndromic cleft lip with or without cleft palate (NSCL±P) in the Brazilian population." (PMID 36661544, 2022).
CNS leukemia (2 papers, 2011 to 2019). "There is an ongoing interest in the question of how the TJ proteins are modified by MMP-2 and -9 as it occurs in CNS leukemia." (PMID 21857898, 2011). "Although reports have shown that MMP-2 and -9 are closely associated with the BBB disruption in some CNS related diseases, little is known about the pathological role of MMP-2 and -9 secreted by leukemic cells in BBB breakdown in CNS leukemia." (PMID 21857898, 2011). "Consistent with MLL/AF6, the human MMP-2 and -9 transcriptions were initially detected at day 21 after being challenged by SHI-1 and amplified in all killed mice with CNS leukemia." (PMID 21857898, 2011). "We hypothesized that MMP-2 and -9 secreted by leukemic cells induced the permeability of the BBB by disrupting the TJ proteins in CNS leukemia." (PMID 21857898, 2011). "In conclusion, our results established a correlation between MMP-2 and -9 secreted by leukemic cells and the disruption of the TJ proteins ZO-1, claudin-5 and occludin, which increases paracellular permeability of leukemic cell across the BBB in CNS leukemia." (PMID 21857898, 2011). "In order to investigate this hypothesis, we examined the relationship of MMP-2 and -9 secreted by leukemic cells with the TJ proteins and the BBB dysfunction in an in vitro model of BBB and in an animal model of CNS leukemia." (PMID 21857898, 2011).
colorectal adenocarcinoma (2 papers, 2014 to 2016). The most common type of colorectal carcinoma. "Thus, MMP-2 expression has been investigated in several cancer types including colorectal adenocarcinoma, as MMP is significantly increased in the tumor tissue compared with the nontumor tissue." (PMID 24737953, 2014).
diabetic macular edema (2 papers, 2020 to 2025). "The action of MMP2 takes part in the breakdown of the blood–retinal barrier by degrading proteins, resulting in increased vascular permeability and blood–retinal barrier disruption, and this breakdown is associated with the occurrence of diabetic macular edema, which is a critical hallmark of DR." (PMID 41009516, 2025). "MMP-2 and MMP-9 are also implicated in the pathogenesis of diabetic macular edema and fibrovascular proliferation with tractional retinal detachment, which are the most common causes of vision loss in patients with DR." (PMID 32403389, 2020).
dysplasia (2 papers, 2012 to 2014). A usually neoplastic transformation of the cell, associated with altered architectural tissue patterns. "A retrospective immunohistochemical study was carried out on 30 clinically and histologically proven cases of leukoplakia with dysplasia and 10 cases of normal buccal mucosa using anti-MMP-2 and anti-TIMP-2 monoclonal antibodies." (PMID 24591757, 2014). "Descriptive statistics with regard to the median frequencies of cells stained for MMP-2 expression revealed interquartile range of 2 : 4 in mild dysplasia, 2 : 15 in moderate dysplasia, and 2 : 25 in severe dysplasia." (PMID 24591757, 2014). "The expression of MMP-2 and TIMP-2 in the basal and parabasal cells of the overlying epithelium as well as in the fibroblasts of the lamina propria in most of the cases of dysplasia has been shown by other investigators." (PMID 24591757, 2014).
dystocia (2 papers, 2023 to 2024). Slow or difficult obstetric labor or childbirth. "Recently, Kalev-Altman showed a pivotal role for MMP-2 in myometrium remodeling during the mammalian parturition process, underlining a novel cause for dystocia due to a loss in MMP-2 activity in the uterine tissue." (PMID 39769454, 2024). "After unraveling the connection between Mmp2 loss and dystocia occurrence, we next set out to determine the effect of Mmp2 loss on the uterus morphology." (PMID 38069145, 2023). "Overall, this analysis suggests that the occurrence of dystocia is largely linked to Mmp2 loss, as well as indicating that the additional loss of the other gelatinase, Mmp9, reduces this phenotype to a certain extent." (PMID 38069145, 2023). "Overall, this study describes a new role for MMP2 in myometrium remodeling during mammalian parturition process, highlighting a novel cause for dystocia due to a loss in MMP2 activity in the uterine tissue." (PMID 38069145, 2023). "Intriguingly, these data show that the loss of one or two alleles of Mmp9 to the Mmp2-KO background (i.e., Mmp2−/−Mmp9+/− and dKO) leads to a somewhat reversed phenotype of a decreased dystocia incidence (40-42.9%) in relation to the rate in the Mmp2−/− females (54.5%)." (PMID 38069145, 2023). "Additionally, both heterozygous Mmp2+/− and Mmp9+/− showed a dystocia rate of 8.3% (2/24 and 1/12, respectively) in the >6 M-old females." (PMID 38069145, 2023). "Hence, we decided to methodologically characterize the occurrence of dystocia in the following genotypes: WT, Mmp2+/−, Mmp2−/−, Mmp9+/−, Mmp9−/−, Mmp2+/−Mmp9+/−, Mmp2−/−Mmp9+/−, Mmp2+/−Mmp9−/− and Mmp2−/−Mmp9−/− (dKO)." (PMID 38069145, 2023). "When breeding the different MMP2/MMP9-null colonies, we frequently observed pregnant females with dystocia." (PMID 38069145, 2023).
embryonal carcinoma (2 papers, 2014 to 2015). A non-seminomatous malignant germ cell tumor characterized by the presence of large germ cells with abundant cytoplasm resembling epithelial cells, geographic necrosis, high mitotic activity, and pseudoglandular and pseudopapillary structures formation. "CD147 induces membrane vesicles secreted from embryonal carcinoma NT2/D1 cells and stimulates MMP-2 production in fibroblasts to promote embryonal carcinoma invasion." (PMID 25268615, 2014).
eosinophilia (2 papers, 2013 to 2014). "In contrast to a marked peribronchial tissue eosinophilia, eosinophils in the airway were remarkably reduced in both MMP-2 and MMP-9-deficient mice." (PMID 25090641, 2014).
epithelial ovarian tumors (2 papers, 2020 to 2022). "The presence of AR together with MMP-2 in the tumor cells is a risk factor to be considered in epithelial ovarian tumors." (PMID 32718331, 2020). "Based on the present results we conclude that MMP-2 located in the epithelium and the stroma are independent prognostic biomarkers for overall survival in epithelial ovarian tumors." (PMID 32718331, 2020). "Based on Cox proportional hazard regression model we demonstrated that MMP-2 located in the epithelium and the stroma are independent prognostic biomarkers for overall survival in epithelial ovarian tumors." (PMID 32718331, 2020).
fetal growth restriction (2 papers, 2024 to 2025). A fetus that does not grow beyond the 10th percentile of conventionally accepted weight for gestational age. "Overexpression of miR-125b-5p led to a decrease in MMP2 levels, impairing the invasive capacity of trophoblasts and potentially contributing to disorders like fetal growth restriction (FGR) and recurrent miscarriage." (PMID 39595182, 2024).
glomerulonephritis (2 papers, 2013 to 2024). A renal disorder characterized by damage in the glomeruli. "In a small study, MMP-2 and -9 levels in the serum of 10 patients with glomerulonephritis paralleled their expressions in kidney biopsy tissues." (PMID 23922934, 2013). "The hypothesis is substantiated by the findings that serum MMP-2 and -9 levels paralleled their expressions in kidney biopsy tissues of 10 patients with glomerulonephritis." (PMID 23922934, 2013).
gouty arthritis (2 papers, 2022 to 2023). "Studies have shown that the activation of MMP2 and MMP9 in GA SF samples can reveal the inflammation of the knee joint in gouty arthritis." (PMID 38066599, 2023).
gynecological cancer (2 papers, 2013 to 2020). "MMP-2 overexpression seems to be associated with poor prognosis in several types of gastrointestinal and gynecological cancers." (PMID 32669083, 2020).
hemangioma (2 papers, 2020 to 2021). A benign vascular lesion characterized by the formation of capillary-sized or cavernous vascular channels. "The concentration of OPG is positively correlated with hemangioma, and it can promote the inflammatory response of vascular smooth muscle cells through cathelicidin S, Matrix metalloproteinase-2 (MMP-2) and MMP-9." (PMID 34901023, 2021). "In vascular endothelial cells, propranolol is considered to induce vascular contraction by suppressing NO production, inhibit renin production, control angiogenesis by regulating the expression of VEGF•bFGF•MMP2/MMP9, and induce apoptosis, but it may also affect pericytes and hemangioma stem cells." (PMID 32202048, 2020).
Hepatic steatosis (2 papers, 2023 to 2024). Steatosis is a term used to denote lipid accumulation within hepatocytes. "Statistically significant, positive correlations between hepatic steatosis and the concentration of MMP-2 (matrix metalloproteinase 2), resistin, and IL-1β in saliva were also found." (PMID 36769216, 2023). "However, statistically significant, positive correlations (p < 0.001; r = 0.37) were observed between hepatic steatosis and the concentration of MMP-2 in saliva." (PMID 36769216, 2023). "Higher median MMP-2 concentrations were found in groups of people with fatty liver compared to groups of people without fatty livers." (PMID 36769216, 2023).
hepatitis B (2 papers, 2016 to 2022). "According to the YZHG-disease association network, the hepatitis B and hepatitis C PPI data in the normal group had a common target, MMP2, with the predicted target of YZHG." (PMID 35342754, 2022). "It is worth noting that the normal group-hepatitis B and hepatitis C protein-protein interaction data share the common target MMP2 with the 5predicted targets of YZHG." (PMID 35342754, 2022). "The results show that hepatitis B and hepatitis C shared a common target, MMP2." (PMID 35342754, 2022).